IL33 (interleukin 33)
Diseases named in the same sentence as IL33 in open-access papers (continued):
Sharing a sentence is not in itself a finding about the gene and the disease.
tumor (continued). "The differentially expressed cytokines between tumor-bearing and tumor-free mice included CSF2, TGFB1, IL33, IL1B, and EGF." (PMID 41214328, 2025). "We also show that DAC epigenetically induces IL-33 expression and that IL-33/ST2 tumor-immune axis is crucial for immune migratory response and anti-tumor effects of DAC." (PMID 40317004, 2025). "The ligand for ST2 is interleukin-33 (IL-33), which binds to ST2L and triggers signaling pathways with immunomodulatory effects across various cell types, including those involved in tumor, immune, and cardiac functions." (PMID 40244022, 2025). "By targeting IL-33, the therapeutic effect of BRCA can be enhanced by regulating excessive immune responses, reducing inflammatory damage, or fighting tumor cells by enhancing immune responses." (PMID 39911848, 2025). "In human mandibular gingival SCC and lymph nodes specimens, the numbers of blood vessels positive for CD34 (a vascular endothelial cell marker), CD105 (a well-established tumor angiogenesis marker), JCAD, and IL-33 were counted." (PMID 41374934, 2025). "Blocking IL-33 or its receptor ST2 inhibits Th9 differentiation from CD4+ T cells, underscoring the importance of this pathway in anti-tumor responses." (PMID 41163402, 2025). "More recently, IL‐33‐induced activation of lung ILC2 was shown to impair NK cell function and increase tumour burden in a model of metastatic lung disease." (PMID 40899118, 2025). "Results from studies in experimental models of malignancy further suggest that intratumoral administration of IL-33 can promote effector T cells infiltration, increase interferon-gamma (IFN-γ) production, and slower tumour growth." (PMID 41284319, 2025). "In summary, the data presented above suggest that IL-33 stimulates the MAPK pathway, which can subsequently lead to activation of the NHEJ pathway in tumor cells and confer resistance to chemotherapeutic drugs." (PMID 40216748, 2025). "Basophils, activated by IL-33, increase the release of several degranulating molecules like CD63 and granzyme-B, leading to tumor cell killing in vitro." (PMID 40305195, 2025). "Although the study identifies IL-33 as a mediator of EMT and metastasis in LSCC, the detailed molecular mechanisms by which IL-33 influences CAF activation and subsequent tumor behavior remain partially understood." (PMID 41272907, 2025). "Currently, research on the IL-33/ST2 pathway covers various aspects, revealing its dual role in diseases, including promoting tumor development and inhibiting tumor invasion and metastasis." (PMID 39925809, 2025). "Clinical studies show that the high expression of IL-33 in paracancerous tissues of NSCLC patients, along with elevated serum levels, correlates with increased tumor malignancy and poor prognosis." (PMID 40426949, 2025). "Staining of PBMC migrated into the Matrigel chambers containing DAC/IL-33 treated A375M, showed the presence of several CD8 T cells in proximity of the tumor cells in all experimental conditions (i.e. vs NT, vs IL-33, vs DAC)." (PMID 40317004, 2025). "Through the TAK1-inhibitor of the kappa B kinase 2 pathway, IL-33 can also induce cancer cell stem cells by activating the JNK or NF-κB pathway, thereby activating the development process of tumor cells." (PMID 39925809, 2025). "The IL-33/ST2 signaling pathway promotes cancer progression and remodels the tumor microenvironment by augmenting immunosuppressive cells." (PMID 40877572, 2025). "Treatment with amphotericin B led to significant reductions in IL-33 secretion, TH2 and ILC2 cells infiltration, and overall tumor burden." (PMID 39044834, 2024). "Recently, an increasing number of published studies have shown that IL-33 can recruit and activate CD8+ T cells and natural killer (NK) cells to inhibit the metastasis of tumor cells." (PMID 38238529, 2024).
tumor (continued). "Mechanistically, immunotherapy stimulates the production of IL-5 and IL-33 by CD4+ T cells, which induces the production of eosinophils in the bone marrow, increased systemic eosinophil circulation, and accumulation in the tumor site." (PMID 39496729, 2024). "IL-33 blockade restricted SCC outgrowth, decreased Th2-derived IL-4 and increased the accumulation of Th1 IFNγ-producing cells in tumour-draining lymph nodes, and thus represents a promising SCC treatment strategy." (PMID 38662248, 2024). "This stromal IL-33 decreases CD8+ T-cell infiltration and activation, consequently facilitating tumor progression." (PMID 39770538, 2024). "Low doses of endogenous IL-33 exert protumor effects by expanding Treg populations, promoting TAM M2 polarization, and directly inducing the proliferation or migration of tumor-prone cells." (PMID 38825642, 2024). "We confirm our earlier discovered inverse correlation between the IL-33/ILC2 alignment and the tumor growth pattern, conducting an in vivo ADT study, utilizing the advantage of tILC2 cell-plasticity." (PMID 38524132, 2024). "Different prognostic clinicopathological features were examined and tissue microarray (TMA) slides were designed to carry out IHC for IL-33 and VEGF scoring in tumor cells, in addition to qualitative interpretation of VEGF expression in tumor vessels." (PMID 38313904, 2024). "Another interesting study comes from Alam and colleagues, who showed that cancer cells produce IL-33, which then triggers the recruitment and activation of TH2 and group 2 innate lymphoid cells (ILC2s), promoting tumor growth in KPC mice." (PMID 39044834, 2024). "Elevated levels of IL-33 in the TIME, through binding to its receptor ST2, lead to the transient accumulation of imported FAs in lipid droplets, inducing ILC2’s pro-tumor activity." (PMID 39119332, 2024). "We observed a robust reduction in tumor growth in the anti-CSF1R and IL-33 + anti-CSF1R groups compared with the control group." (PMID 38238529, 2024). "In preclinical models, IL-33 has been shown to support the recruitment and activation of cytotoxic NK cells in the TME, which hinders the formation of metastasis and suppresses tumor progression." (PMID 40236667, 2024). "For example, IL-33 can activate ILC2 in the lung, which promotes tumor burden by leading to innate type 2 inflammation and suppressing the production of IFN-γ and the cytotoxic functions of lung NK cells." (PMID 40236667, 2024). "In in vitro CD8+ T-cell culture, IL-33 promoted T-cell activation and IFN-γ expression, which suppressed tumor growth." (PMID 38825642, 2024). "Surprisingly, intratumoral fungi like Alternaria alternata can promote IL‐33 secretion from PDA cells, and both M. globosa and A. alternata promote tumor growth simultaneously." (PMID 38882486, 2024). "Conversely, IL-33 signaling encourages the proliferation of suppressive CD4+ Foxp3+ GATA3+ Treg cells, especially in tumor-specific environments high in IL-33." (PMID 40236667, 2024). "Our study emphasized the role of IL6high CAF on tumor cells for elevating level of various cytokine genes including IL6, IL32, IL33, CXCL1, CXCL3 and CXCL8, and oncogenic pathways, such as the Wnt and VEGF signaling pathways." (PMID 38892065, 2024). "This characteristic of IL-33 helps maintain the immune microenvironment in a relatively balanced and stable state, avoiding inflammatory injury of tissues and organs; this is also one of the reasons why some studies believe that IL-33 may promote tumor progression." (PMID 38238529, 2024). "In tumor immunotherapy utilizing these IL-33-induced FCGR3+CD103+ cDC1s, tumor growth in solid tumor models or lung metastasis tumor models is significantly suppressed compared to that in control cDC1s or GM-CSF-induced CD103+ cDC1s31." (PMID 38825642, 2024). "Conversely, the IL-33/ST2L axis modulates the TME, recruiting immune cells and improving anti-tumor immunity." (PMID 38778059, 2024).
tumor (continued). "IL33 drives MMP9 production via an NF-kB-dependent mechanism, leading to laminin degradation, which can be a critical step for tumor cell extravasation and invasion (path 2)." (PMID 39086395, 2024). "To abolish the pro-tumor effects of IL-33/ST2L signal in TME, we generated IL-33-neutralizing (α-IL-33) and ST2L-neutralizing antibody (α-ST2L) and examined their effects on macrophage polarization." (PMID 38778059, 2024). "Our pre-clinical evidence supports targeting pro-tumor cytokine IL-33 and its receptor ST2L as an effective strategy to convert the immune-evasive TME to immunoreactive TME for tumor therapy." (PMID 38778059, 2024). "A crucial aspect of IL-33’s impact lies in its ability to inhibit MDSC differentiation, thereby promoting a robust tumor immune response within the ascitic environment." (PMID 38881897, 2024). "This capacity of IL-33 plays a pivotal role in shaping the tumor microenvironment (TME) and influencing tumor growth." (PMID 38881897, 2024). "These cytokines derived from IL-33-activated basophils are essential for the generation of FCGR3+CD103+ cDC1s, which prime tumor-specific CD8+ T cells." (PMID 38825642, 2024). "As we expected, RRM2, SLC2A1, DDIT4, and VDAC2 were significantly upregulated transcriptionally and translationally in tumor samples, whereas PEBP1 and IL33 are significantly reduced in tumorous tissues." (PMID 39311766, 2024). "When this binding occurs in the presence of IL-18, IL-33, and IFN-γ, eosinophils release TNF-α, granzyme A, ROS, nitric oxide, and eosinophil extracellular traps (EETs) to kill the tumor cell." (PMID 38892286, 2024). "In summary, IL33's biological functions in HCC, as indicated by GSEA, point towards its involvement in promoting cancer stemness, affecting tumour progression, modulating the immune microenvironment, and contributing to genomic instability." (PMID 38923705, 2024). "The IL-33 and VEGF expressions were also estimated within the tumor cells and the expression of the later one was assessed within the vascularity of the tumor." (PMID 38313904, 2024). "Conversely, the genetic deletion of IL-33 or antifungal therapy results in the regression of stable pancreatic ductal adenocarcinoma (PDAC), underscoring the tumor-promoting nature of Th2 cells." (PMID 38840908, 2024). "In the context of GM-BMDC-based tumor immunotherapy, IL-33 administration reportedly drives the induction of IL-9-producing CD8+ T cells, potentiating the inhibition of tumor growth." (PMID 38825642, 2024). "Eosinophils seem to react differently to various mediators, including IFN-γ, IL-5, IL-33, CCL1124,43–46, and tumor-derived TSLP47, resulting in either enhanced cancer cell killing or promotion of tumor growth." (PMID 38951159, 2024). "In recent years, increasing attention has been given to the role of IL-33/ST2 in tumorigenesis and development, but the effect and mechanism of IL-33/ST2 on tumor progression are still controversial." (PMID 37507682, 2023). "IL-33/ST2L axis promotes chemoresistance and sphere formation and stimulates in vivo tumor growth, both in human and murine colon cancer cells, with the expression of the core stem cell genes NANOG, NOTCH3, and OCT3/4." (PMID 37296602, 2023). "Based on these findings, they concluded that intra-tumoral fungi or fungal products provoke IL-33 secretion by PDAC cells, which promotes type 2 immune responses and tumor progression in this PDAC subset." (PMID 37034706, 2023). "Among these is IL-33, a potent emerging modulator of the TME through the recruitment of immune cells able to shape tumor phenotype and promote malignancy or impose tumor regression." (PMID 37296602, 2023). "Nuclear FAK has been shown to promote tumor progression by regulating the transcription of cytokines/chemokines, including CCL5, TGFβ2, IL33, and VEGFβ, which in turn drive the establishment of an immunosuppressive microenvironment." (PMID 37845206, 2023).
tumor (continued). "The mRNA levels of CCR2, CCL2, VEGF, NF-κB, c-Myc, vimentin, and IL33 were determined in the CT26 cell line and then tumor tissues (after 21 days), by qRT-PCR." (PMID 37325423, 2023). "IL-33 was the most significant DEG involved in these processes and was significantly upregulated in 5-FU-sensitive tumor tissues." (PMID 37056569, 2023). "To determine how IL-33 derived specifically from the epithelium contributes to early neoplasia, we developed a GEMM that enables specific Il33 suppression in lineage-traced Kras-mutant epithelial cells." (PMID 37167403, 2023). "Accordingly, we also found a positive correlation between IL-33 expression and CD3+ T cell infiltration in CRC tumor tissues." (PMID 37056569, 2023). "Among which, IL‐33 recognizes the receptor ST2 in Foxp3+ Tregs, then promoting the Foxp3+ Tregs accumulation and immunosuppressive functions in tumor." (PMID 36226375, 2023). "Members of the IL1 family, including IL1B, IL33, and IL18, are upregulated in the GPBAR1 tumors and are generally identified as contributors to tumor immunosuppression." (PMID 36834607, 2023). "Eosinophil mediators, such as IL-5, IL-33, granulocyte–macrophage colony-stimulating factor (GM-CSF), thymic stromal lymphopoietin (TSLP), and CCL11 also determine eosinophil behavior toward tumor cells." (PMID 37587450, 2023). "Some believe that the expression level of IL-33/ST2 is elevated in most tumors (both serum and tumor tissue) and is positively correlated with tumor progression." (PMID 37507682, 2023). "Similar results were achieved in another study where IL-33 activated NK cells in the blood and recruited them to the TME through CCL5 to suppress metastatic tumor development." (PMID 37587450, 2023). "ILC2 triggered by IL33 expresses CCL5 selectively, attracts CD103+ DCs into tumor, and stimulates CD8+ T cells to induce therapeutic tumor immunity." (PMID 37937304, 2023). "Another study suggested that there is also a decrease in the expression level of IL-33/ST2 in tumors (including serum and tumor tissue), and it is negatively correlated with tumor progression." (PMID 37507682, 2023). "It was recently reported that tumor-derived IL-33 increases FcεRIα+ ST2+ macrophages and TGF-β secretion, which promote IL-33 expression in the tumor, followed by invasive tumor progression." (PMID 37246159, 2023). "The upregulation and secretion of interleukin-33 (IL-33) in KRASG12D PDAC subtype cells, and the interaction of these cells with intra-tumor fungi was reported." (PMID 37910468, 2023). "Unsurprisingly, effective tumor control required high numbers of TCF1neg effector CD8+ TILs, a condition met solely following PD1d/IL-2v/IL-33 ACT, where 75–90% of OT1 TILs were TCF1neg." (PMID 37081150, 2023). "Further investigation showed that IL-33 is not only an inducer of CCL11 production and a protector against DPP4, but it also increases eosinophil-mediated tumor cytotoxicity." (PMID 37587450, 2023). "In ICB + CIS cases with the highest intra-tumoral eosinophil penetration, IL-33 and then TSLP were the most increased cytokines in the blood and tumor." (PMID 37587450, 2023). "Accumulation of SCF were observed in tumor lesions compared with tumor-free tissue (colon AOM/DSS) and inflamed colon tissue (colon DSS), while high levels of IL-33 were detected on both inflamed and tumor lesions." (PMID 37730723, 2023). "And IL-33 can stimulate the production of cytokines (IL-4, IL-6) and chemokines (CCL2, CCL3, CCL7, CXCL1), which are also involved in the construction of the tumor microenvironment." (PMID 36110250, 2022). "Many clinical studies show that the high expression of IL-33 in the paracancerous tissues of NSCLC patients and its high level in the serum indicate higher tumor malignancy and poor prognosis." (PMID 35634336, 2022).
tumor (continued). "In the past decade, emerging studies have begun to uncover the previously unappreciated role of IL-25 and IL-33 in CRC disease pathogenesis and in shaping the tumour niche, with distinct effects specific to the different subtypes of CRC." (PMID 36263033, 2022). "IL-33, Adiponectin, CCL8, GRO, and CCL2 contributed to the juxta-tumor type; the other analytes contributed to the tumor type." (PMID 36539890, 2022). "The data in the present study describes the ability of cannabigerol to increase IL-33 expression and uncover a potential method by revive IL-33 expression and ILC2 function leading to enhanced CTL responses against tumours." (PMID 36923728, 2022). "Maintaining immunosuppression functions in the tumour milieu, presence of IL-33 increased TGF-β1 producing MDSCs and reduced IFN-γ expressing NKp46 + tumour lysing cells." (PMID 35557940, 2022). "sST2, a soluble form of the IL-33 receptor, can neutralize IL-33 in TME, thereby suppressing tumor growth, metastasis and tumor angiogenesis." (PMID 35720302, 2022). "Treg-specific ST2 deletion enhances tumor-infiltrating CD8+ T cells in a mouse lung adenocarcinoma model, supporting the idea that IL-33/ST2 signaling-activated Treg cells exhibit pro-tumorigenic functions." (PMID 36291105, 2022). "The role of IL-33 in tumor development has been mostly studied in the context of CRC and current data suggests that IL-33 can contribute to the pathogenesis as well as the suppression of CRC development." (PMID 36032129, 2022). "MDSCs are recruited and activated by IL33, and produce VEGF, FGF, and MMP9 for inducing angiogenesis and tumor invasion in collaboration with other ST2+ cells, including Mø and mast cells." (PMID 36211375, 2022). "The secreted IL-33 recruited and activated Th2 and innate lymphoid cells 2 (ILC2) in the tumor microenvironment (TME), which stimulated tumor growth by secreting pro-tumor cytokines, such as IL-4, IL-5, and IL-13." (PMID 35910636, 2022). "Consistent with elevated levels of IL-33, the ILC2 number per whole lung tissue was found to be higher in the 4T1/LM4 tumor-bearing mice than in the tumor-free mice." (PMID 35805039, 2022). "IL-33 induces basophils to increase expression of a degranulation marker (CD63) and granzyme B, enhancing tumor-killing ability in vitro." (PMID 36291105, 2022). "We also found evidence to support a role for IL-33 in promoting expansion of key mast cell subsets, including CTMC, which typically accumulate at tumour margins and are reactive to toluidine blue staining." (PMID 35677533, 2022). "Despite significant evidence of pro‐tumorigenic role of TECs secreted IL‐33 in CRC by inhibiting anti‐tumor immunity, remodelling tumor stroma, and enhancing angiogenesis, few studies have reported the anti‐tumorigenic effect of IL‐33 in CRC as well." (PMID 35791509, 2022). "IL-33, by biding to its receptor ST2, stimulates in vivo growth of CRC cells both in human and murine and their sphere formation and inhibits tumor apoptosis induced by chemotherapy." (PMID 35611243, 2022). "Notably, it was found that the intratumoral mycobiome can promote the production of IL-33 from cancer cells and subsequently enhance the recruitment and activation of Th2 cells and innate lymphoid cells in the microenvironment of pancreatic cancer, thus inhibiting the progression of the tumor." (PMID 36131933, 2022). "Mast cells are recruited by the microenvironmental chemokines, such as CCL2, CXCL1, CXCL8/IL8, and CXCL10, to tumor tissues, and are activated by pro-inflammatory cytokines, such as stem cell facto (SCF), IL33, PGE2, leukotriene B4, and osteopontin, in there." (PMID 36211375, 2022). "However, in our study, a direct implant of rIL-33 in the developing tumor, which we believe well represents elevated IL-33 levels in the tumor microenvironment, led to increased T cell response and decreased tumor growth suggestive of a global role of IL-33 in activating antitumor immunity." (PMID 36256464, 2022).